GSK3A (glycogen synthase kinase 3 alpha)
Diseases named in the same sentence as GSK3A in open-access papers (continued):
Sharing a sentence is not in itself a finding about the gene and the disease.
diabetic nephropathy (1 paper, 2019). "Podocyte GSK3α knockdown did not have a protective effect on the progression of STZ‐induced diabetic nephropathy but it is possible that this result was due to incomplete knockdown of GSK3α in our transgenic mouse model." (PMID 31825015, 2019).
dilated cardiomyopathy (1 paper, 2018). Cardiomyopathy which is characterized by dilation and contractile dysfunction of the left and right ventricles. "Cardiac myocyte-specific deletion of GSK3α and GSK3β, together, results in severe dilated cardiomyopathy." (PMID 29504933, 2018).
endothelial dysfunction (1 paper, 2023). In vascular diseases, endothelial dysfunction is a systemic pathological state of the endothelium (the inner lining of blood vessels) and can be broadly defined as an imbalance between vasodilating and vasoconstricting substances produced by (or acting on) the endothelium.
Ewing sarcoma (1 paper, 2015). A small round cell tumor that lacks morphologic, immunohistochemical, and electron microscopic evidence of neuroectodermal differentiation. "For example, no GSK-3α selective inhibitors were represented in the library and pan-GSK3 inhibitors represented in the library might fail to yield a relative sensitivity in Ewing sarcoma." (PMID 26337082, 2015).
familial Alzheimer disease (1 paper, 2014). A degenerative disease of the brain that causes gradual loss of memory, judgment, and the ability to function socially. "Lithium, a specific inhibitor of GSK-3α and GSK-3β, reduces Aβ production by interfering with APP cleavage at the γ-secretase step and is found to reduce Aβ production in the mice expressing pathogenic familial Alzheimer's disease." (PMID 24983010, 2014).
fibrosis (1 paper, 2025). the formation of excess fibrous connective tissue in an organ or tissue in a reparative or reactive process. "miR-185–5p, which is up-regulated in GSK-3α-overexpressing cells, has been linked to the promotion of cardiac fibrosis, particularly in patients with sudden cardiac death." (PMID 40836599, 2025).
glomerular disease (1 paper, 2019). "In conclusion we have shown that partial or near‐total suppression of podocyte GSK3α is not protective in models of glomerular disease; its loss is, in fact, detrimental and is associated with impaired autophagic flux." (PMID 31825015, 2019). "Collectively this work shows that GSK3α is important for podocyte health and that augmenting its function may be beneficial in treating glomerular disease." (PMID 31825015, 2019).
head and neck squamous cell carcinoma (1 paper, 2018). A squamous cell carcinoma that arises from any of the following anatomic sites: lip and oral cavity, nasal cavity, paranasal sinuses, pharynx, larynx, and salivary glands. "Analyzing the role of the remaining GSK3 activity in head and neck squamous cell carcinoma, cells were incubated with 10 and 30 μM of the specific GSK3α/β inhibitor SB 216763, respectively." (PMID 29963225, 2018).
Hyperglycemia (1 paper, 2023). An increased concentration of glucose in the blood. "Hyperglycemia reduced the expression of IRs; downregulated mediators of the insulin signaling pathway, including p-PI3K, p-GSK-3α/β, and p-Akt, in the cerebral cortex; and contributed to the loss of cognitive function." (PMID 37443762, 2023).
hyperlipidemia (1 paper, 2019). "Regarding body weight, a double knockdown of both Gsk3a and Gsk3b led to a decrease in body weight, whereas an overexpression of human GSK3B in mice skeletal muscle resulted in impaired glucose tolerance, hyperlipidemia and an increase in fat mass and body weight gain." (PMID 31801236, 2019).
ischemic heart disease (1 paper, 2025). "The observations suggest that GSK-3α-mediated miRNA dysregulation may significantly contribute to the signaling pathways involved in pathological changes during ischemic heart disease." (PMID 40836599, 2025). "The potential relationship between GSK-3α and miRNA regulation may provide new insights into the molecular basis of ischemic heart disease." (PMID 40836599, 2025).
kidney damage (1 paper, 2019). "We suspect that in some patients receiving lithium there is excessive suppression of GSK3α/β activity in their podocytes and this leads to glomerular and kidney damage." (PMID 30679422, 2019).
liver cirrhosis (1 paper, 2025). "In addition, upregulation of STK4 and GSK3α was also observed in the liver cirrhosis patients by immunohistochemistry staining." (PMID 40368138, 2025).
liver diseases (1 paper, 2025). "Glycogen synthase kinase 3 (GSK3) is a multifunctional serine/threonine kinase with two isoforms, GSK3α and GSK3β, that regulate glycogen synthesis and glucose metabolism, with GSK3β being particularly implicated in liver diseases." (PMID 40004939, 2025).
microphthalmia (1 paper, 2021). Congenital or developmental anomaly in which the eyeballs are abnormally small. "We showed that complete loss of both GSK3s severely impacts retinal morphology with microphthalmia phenotype, which could be completely rescued with the expression of just one Gsk3α or Gsk3β wild-type (WT) allele." (PMID 34518365, 2021).
mouth neoplasms (1 paper, 2015). "The present study revealed an increased protein expression of GSK3β compared to GSK3α in various types of mouth neoplasms." (PMID 25645517, 2015).
mucoepidermoid carcinoma (1 paper, 2015). A carcinoma morphologically characterized the presence of cuboidal mucous cells, goblet-like mucous cells, squamoid cells, cystic changes, and a fibrotic stromal formation. "The tissue samples of most of the mucoepidermoid carcinoma showed expression of both GSK3α and GSK3β in ductal cells (c, d and q, r and u, v)." (PMID 25645517, 2015). "Mucoepidermoid carcinoma and normal salivary glands exhibited expression of GSK3α and GSK3β, mainly in the ductal cells." (PMID 25645517, 2015).
Myocardial fibrosis (1 paper, 2021). "Future studies are warranted in order to further validate the GSK-3α-ERK-IL-11 signaling circuit as a therapeutic target for the management of myocardial fibrosis." (PMID 34572061, 2021). "In stark contrast, the FB-specific deletion of GSK-3α protected against TAC-induced myocardial fibrosis and cardiac dysfunction." (PMID 34572061, 2021).
pancreatic ductal adenocarcinoma (1 paper, 2020). An infiltrating adenocarcinoma that arises from the epithelial cells of the pancreas. "The preferential activity of GSK3α over GSK3β in cancer cells has also been reported in pancreatic ductal adenocarcinoma (PDA), in which GSK3α, but not GSK3β, promotes activation of the canonical and non-canonical NF-κB pathways to promote cell viability and apoptosis resistance." (PMID 33339170, 2020).
primary angle-closure glaucoma (1 paper, 2024). An angle-closure glaucoma characterized by closure of the anterior chamber angle by an intrinsic defect such that aqueous outflow is blocked and the intraocular pressure becomes inappropriately elevated leading to optic nerve damage and visual field loss. "It has been suggested that PCK2 gene mutation causes primary angle-closure glaucoma (PACG) by disrupting the AKT/GSK3α signaling pathway." (PMID 38890507, 2024).
progeria (1 paper, 2023). "Interestingly, progeria‐specific mechanisms in the Aging map, involving SREBF1, GSK3A/B, and FBXW7, are related to PGC1A activity in the PD map, indicating potential cell and tissue specificity of the mechanism." (PMID 36648161, 2023).
pulmonary TB (1 paper, 2024). "Phosphorylation of CREB, a transcription factor controlling gluconeogenesis was drastically reduced in the livers of mice with pulmonary TB as was phosphorylation of other glucose metabolism-related kinases, including GSK3a, AMPK, and p42." (PMID 39331683, 2024).
renal carcinoma (1 paper, 2009). A carcinoma arising from the epithelium of the renal parenchyma or the renal pelvis. "To determine whether the inhibitory effect on renal cancer cell survival by pharmacological inhibition of GSK-3 was specific to GSK-3β, we depleted GSK-3α or GSK-3β expression in ACHN cancer cells using siRNA." (PMID 19920820, 2009). "We found that depletion of GSK-3β leads to a significant decrease in renal cancer cell survival accompanied with apoptotic morphological changes as detected by Hoechst staining, whereas depletion of GSK-3α does not affect cancer cells." (PMID 19920820, 2009). "Moreover, we show that depletion of GSK-3β by siRNA leads to a decrease in renal cancer cell survival, suggesting that GSK-3β, but not GSK-3α, is a selective regulator of survival in renal cancer cells." (PMID 19920820, 2009).
respiratory infections (1 paper, 2025). "This study identifies GSK3A as a key host kinase that promotes human adenovirus replication and phosphorylates viral protein L4-22K, revealing a potential therapeutic target for treating HAdV-related respiratory infections." (PMID 40537285, 2025).
rheumatoid arthritis (1 paper, 2021). A chronic, systemic autoimmune disorder characterized by inflammation in the synovial membranes and articular surfaces. "A previous study suggests that GSK3α/β inhibitors could be used as anti-inflammatory drugs to treat the rheumatoid arthritis (RA)." (PMID 33672232, 2021).
SARS-CoV-infection (1 paper, 2023). "There were insufficient sections with blood vessels to quantify staining with the required statistical rigor to determine if phosphorylated GSK3α/β levels changed in the postinfection time frame or if there were sex differences following SARS-CoV-infection." (PMID 37737732, 2023).
skin cancer (1 paper, 2024). "ASIP was colocalized with all three types of skin cancer and STX8, KRT5, GSK3A, CTSS, and TNFSF8 with BCC." (PMID 39003418, 2024).
squamous cell carcinoma (1 paper, 2016). A carcinoma arising from squamous epithelial cells. "However, positive GSK3A expression was not significantly correlated with shorter survival time of the patients with squamous cell carcinoma histology type." (PMID 27049759, 2016).
tongue SCC (1 paper, 2025). "A study by Huang et al24stated that in human tongue SCC SAS cells, quercetin induces apoptosis and mitochondrial damage through the JNK, ERK1/2, and GSK3-α/β signaling pathways." (PMID 39348855, 2025).
Wilms tumor (1 paper, 2020). An embryonal neoplasm characterized by the presence of epithelial, mesenchymal, and blastema components. "Here we show that the glycogen synthase kinase 3 alpha/beta (GSK3A/B) inhibitor CHIR99021 significantly represses ALDH1A2 expression in WiT49, which is a Wilms’ tumor cell line that exhibits “triphasic” differential potential and is used as a fetal kidney cell model." (PMID 32258025, 2020).
ZIKV infection (1 paper, 2022). "Together, ZIKV infection showed the pathology of accelerated p-Tau and elevated GSK3α/β expression as one of the underlying mechanisms." (PMID 35368019, 2022).
tumor (58 papers, 2011 to 2026). "GSK3A is found as a member of the Wnt/β-catenin pathway; its activation is usually observed in malignancies and is associated with cell processes and tumor recurrence, indicating its involvement in the evolution of cancers." (PMID 34607506, 2022). "Our studies of GSK3α/β isoform expression suggest that cell lines have a skewed isoform and splice variant expression compared to primary tumor tissue, which is important to take into account." (PMID 28968964, 2017). "Next, we conducted IHC assays to investigate the micro-vessel density of tumors in the four groups and found that GSK3α markedly promoted tumor angiogenesis, although this could be inhibited by loss of HIF1α." (PMID 35292059, 2022). "Levels of GSK3α expression in clinical samples were detected using western blot and IHC assays, while its biological function and underlying mechanism of action in tumor progression were investigated using western blot, CCK8, cell cycle, colony formation, Transwell, ELISA and tube formation assays." (PMID 35292059, 2022). "Collectively, our results highlight the distinct role of GSK-3 isoforms in the regulation of NK cell reactivity against target cells and suggest that GSK-3α modulation could be used to enhance tumor cell susceptibility to NK cells in an NKG2D- and NKp30-dependent manner." (PMID 33918810, 2021). "We found that phosphorylation of GSK3a was significantly higher in palbociclib treated tumours (one-cycle) compared to vehicle (p = 0.02), demonstrating an inhibitory effect on the cell cycle during the first cycle of treatment." (PMID 37190140, 2023). "To further validate the novel role of GSK3α in tumor angiogenesis, we cultured endothelial cells (HUVECs) in conditional media (CM) from NSCLC cells expressing shnc or shGSK3α, then performed CCK8 assay." (PMID 35292059, 2022). "Collectively, these data strongly implied that GSK3α regulated tumor angiogenesis via the HIF1α/VEGFA signaling pathway." (PMID 35292059, 2022). "Taken together, these observations showed that GSK3α-mediated tumor angiogenesis depends on HIF1α expression." (PMID 35292059, 2022). "Results from in vivo assays proved that GSK3α-mediated tumorigenesis and tumor angiogenesis is dependent on levels of HIF1α expression." (PMID 35292059, 2022). "Overall, the GSK-3β isoform appeared to be dominant over the GSK-3α isoform, although both isoforms were needed for optimal tumor rejections." (PMID 34142056, 2021). "In the present study, our data showed that apatinib inhibited tumor progression by negatively regulating the AKT/GSK3α/β pathway in GC." (PMID 34453028, 2021). "Although it requires further assessment of dead tumor cells among the peritoneal cells, these results suggest that GSK-3α inhibition in TKI-resistant KCL-22M cells enhances NK cell-mediated surveillance in vivo." (PMID 33918810, 2021). "At the same time, long-term inactivation of GSK-3α/β by SB415286 enhanced the tumor killing potency of the resultant cytolytic mouse T-cells." (PMID 34975828, 2021). "Taken together, we found that pharmacological inhibition and gene silencing of GSK3α/β selectively induced apoptosis and inhibited tumor growth of mutant KRas-dependent tumors, which was at least in part mediated by c-Myc and β-catenin." (PMID 30514931, 2018). "An important finding of our studies is that suppression of GSK3α/β inhibits mutant KRas-dependent tumor growth at least in part by a c-Myc- and β-catenin-dependent mechanism." (PMID 30514931, 2018). "In summary, the novel mechanism presented here opens new avenues to therapeutically target mutant KRas-dependent human cancers by suppressing GSK3α/β, leading to β-catenin- and/or c-Myc-dependent tumor abrogation." (PMID 30514931, 2018). "In this manuscript, we revealed that human tumors dependent on mutant KRas require GSK3α/β for viability, survival, and tumor growth." (PMID 30514931, 2018).
tumor (continued). "Tideglusib displayed pharmacokinetic potency in reducing GSK3β-mediated phosphorylation of phospho-β-catenin and consequent increase in total β-catenin in vitro for primary tumor cultures with demonstrated over-expression of GSK3α and GSK3β." (PMID 28968964, 2017). "We next addressed the role GSK-3α in tumor growth in vivo using subcutaneous injections of control or GSK-3α-depleted cells." (PMID 27049759, 2016). "Detectable expression of GSK3α was observed in 83.3% normal (5/6), 66.6% PMLs (4/6), and 51.8% tumor samples (14/27)." (PMID 25645517, 2015). "Alternatively, among the five (5/14) positive tumors of a higher grade (MDSCC and PDSCC), the expression of GSK3α was observed in the NC, N-CC and CC in 2, 2 and 1 of the tumor samples, respectively." (PMID 25645517, 2015). "The expression of total GSK3α/β in the tumor samples generally increased from the normal expression level but a small fraction of the tumor tissue also showed the opposite trend." (PMID 25645517, 2015). "All of these independent observations demonstrate a higher expression level of GSK3β than GSK3α in oral tumor tissue samples." (PMID 25645517, 2015). "This once again support our findings that GSK3α-mediated cell survival and proliferation promotes tumor growth in both early and advanced stages, and that GSK3β/β-catenin-mediated EMT promotes cell motility, invasion and micrometastasis in the advanced stages." (PMID 25714023, 2015). "Many components of the Wnt/β-catenin signaling pathway have critical functions in mammary gland development and tumor formation, yet the contribution of glycogen synthase kinase-3 (GSK-3α and GSK-3β) to mammopoiesis and oncogenesis is unclear." (PMID 25195860, 2015). "Phosphorylation of GSK3α/β at the inhibitory S21/9 residue was a poor biomarker for activity in tumour samples." (PMID 25486534, 2014). "Complete loss of GSK3 causes intestinal defects, whereas individual deletion of GSK3α or GSK3β preserves normal intestinal structure and survival without tumor development." (PMID 41300341, 2025). "Overall, these results demonstrated that GSK3α-inducing tumor angiogenesis was dependent on HIF1α." (PMID 35292059, 2022). "In the current study, GSK3A expression was found to be enhanced in tumor tissues." (PMID 34607506, 2022). "Results from analysis of tumor images and animal weights further confirmed that GSK3α promoting tumor growth could be inhibited by silencing of HIF1α." (PMID 35292059, 2022). "Analysis of tumor growth curve showed that cells expressing GSK3α + shnc grew faster than those expressing vector + shnc, while GSK3α promoting tumor growth could be inhibited by silencing of HIF1α." (PMID 35292059, 2022). "Additionally, miR-485-5p targeted GSK3A in GC, whose expression was elevated in tumor tissues and was negatively correlated with miR-485-5p in tumor cells." (PMID 34607506, 2022). "Although these studies suggest that both GSK-3α and GSK-3β isoforms are oncogenic in GBM, a tumor suppressor role for GSK-3α has also been proposed in GBM by which it promotes apoptotic alternative splice events, though this remains incompletely defined and warrants further investigation." (PMID 33525562, 2021). "High phosphorylation levels of GSK-3α/β indicates lower activity of this kinase in the tumor cells." (PMID 29187162, 2017). "Knockdown of GSK-3α attenuates cell viability, colony formation, and tumor growth." (PMID 27049759, 2016). "Inhibition of GSK-3α suppressed cell viability, colony formation, and tumor growth." (PMID 27049759, 2016). "Consistent with our hypothesis and data, GSK-3α knockdown resulted in a significant suppression in tumor growth and tumor volume." (PMID 27049759, 2016). "Next, we determined if GSK3α knockdown also affect tumor cell proliferation in vivo." (PMID 25714023, 2015). "The inactive phosphorylated forms of GSK-3α/β were increased in tumor-bearing livers." (PMID 24691449, 2014).